MMP9 (matrix metallopeptidase 9)
Diseases named in the same sentence as MMP9 in open-access papers (continued):
Sharing a sentence is not in itself a finding about the gene and the disease.
Sepsis (continued). "However, we must note the apparent contradiction with a previous report of positive correlation between MMP-9 and APACHE-II score in sepsis patients." (PMID 19799791, 2009). "MMP-9 and TIMP-1 are key regulators of inflammation, and disturbances in their dynamic balance of expression and activity may contribute to tissue damage and increased mortality in sepsis." (PMID 38337856, 2024). "However, in the context of various pathogenic microorganisms, different immune microenvironments, different organs and tissues, and different clinical syndrome phenotypes of sepsis and VTE, the specific function and mechanism of MMP9 are still poorly understood." (PMID 38029239, 2023). "Among them, MMP9 was differentially expressed in the sepsis survivor-sepsis non-survivor group (SS-SN), indicating that MMP9 may be related to the prognosis of sepsis." (PMID 36406124, 2022). "Therefore, in severe sepsis, BBB dysfunction is related to the activities of MMP-2 and MMP-9." (PMID 35295600, 2022). "Interestingly, the mean MMP-9 concentration in the group questionable for sepsis was lower than in the negative group, which was visible in plasma and peritoneal fluid." (PMID 33488296, 2021). "During the calculation of optimal cutoff values for MMP-9 concentration in plasma and peritoneal fluid, it became obvious that these would be quite low in comparison with mean values in horses scoring negative or questionable for sepsis." (PMID 33488296, 2021). "Collectively, these findings let us suggest that increased MMP-9-mediated sRAGE production may represent a self-protective mechanism in response to sepsis, whereas exogenous enhancement of sRAGE levels is not sufficient to improve survival." (PMID 33628393, 2021). "A more detailed comment on the role of these biomarkers in septic AKI could be found in our earlier paper, but clinical reports on MMP-9 and TIMP-1 in sepsis-associated liver injury are lacking." (PMID 29861795, 2018). "Similarly, MMP-9 deletion protects mice from endotoxic shock and sepsis; therefore, MMP-9 inhibition has been proposed as a potential therapeutic approach to treat human sepsis." (PMID 28852269, 2017). "Despite the abundance of literature in animal and human models describing the association of elevated MMP-9 levels with two distinct entities such as hyperglycemia and sepsis, the link between BG and MMP-9 levels in humans with severe sepsis and septic shock has not been described." (PMID 27110221, 2016). "However, the MMP-9 and MMP-9/TIMP-1 ratio was not significantly higher in severe sepsis and septic shock than in sepsis, or in septic shock than in severe sepsis." (PMID 25407832, 2014). "MMP9 has been shown to have negative correlation with multiple organ dysfunction scores in sepsis." (PMID 24612859, 2014). "The small number of healthy controls may have contributed to the absence of significant differences in MMP-9 levels between the sepsis patients and these healthy controls." (PMID 19799791, 2009). "The relatively small sample size of the control group may have contributed to the absence of significant differences in MMP-9 levels between controls and sepsis patients." (PMID 19799791, 2009). "Moreover, we found that CD3, CD247, CD2, and CD40LG were negatively correlated with KC, whereas MMP-9, LCN2, and RETN were positively correlated with KC, suggesting that these candidate hub genes may regulate geriatric sepsis-induced ARDS by modulating the recruitment of neutrophils to the lung." (PMID 37822934, 2023).
Sepsis (continued). "Finally, the expression of the topmost upregulated genes (ARG1, IL1R2, ELANE, MMP9) was quantified by reverse transcriptase-PCR (RT-PCR), and myeloperoxidase (MPO) expression was confirmed by immunohistochemistry (IHC) staining in the lungs of a well-established sepsis mouse model." (PMID 31817302, 2019). "Patients with sepsis had lower levels of MMP-9 on admission to SICU and 24 h later than nonoperated controls, but such levels of MMP-9 were similar to those in operated controls." (PMID 29861795, 2018). "Respectively, a study has been reported that in patients with gram-negative bacteria, the severity of sepsis depends on the increasing levels of pro-MMP-9, pro-MMP-2, and the activated forms of MMP-9." (PMID 30142934, 2018). "Our study suggests that the prognostic value of NGAL, MMP-9 or TIMP-1 is superior to PCT and MEDS score, and that NGAL, TIMP-1, MMP-9 or MEDS score, but not PCT, are robust independent predictors of 28-day death in patients with sepsis." (PMID 25407832, 2014). "Previous clinical studies including our own have shown higher circulating levels of MMP-9 and TIMP-1 in septic patients than in controls, and higher levels of TIMP-1 at the time of severe sepsis diagnosis in non-surviving than in surviving patients." (PMID 24727739, 2014). "The area under the ROC curve for MMP-8 in the diagnosis of sepsis was 0.87 (95% CI 0.82–0.92), and that of CRP was 0.98 (0.94–0.998), whereas the area of MMP-9 in the detection of non-septic state was 0.73 (0.65–0.80), p < 0.0001 for all curves." (PMID 24833564, 2014). "Hoffmann and colleagues, demonstrated elevated plasma levels of MMP-9 and tissue inhibitors of matrix metalloproteinases (TIMP)-2, and TIMP-1 on the first day of severe sepsis and significantly higher TIMP-1 levels in non-surviving patients." (PMID 20356362, 2010). "The interesting finding that MMP-9 levels were higher in non-survivor sample in the blister fluid at only the first day might be due to sepsis-induced damage on the structures of healthy looking skin, observed clinically as edema and even as spontaneous blistering in most severe forms of sepsis." (PMID 20356362, 2010). "Small clinical studies (with fewer than 40 patients) have shown higher plasma levels of MMP-9 and TIMP-1 in sepsis patients as compared with those observed in controls, and higher levels of TIMP-1 or MMP-9 in nonsurviving than in surviving patients." (PMID 19799791, 2009). "Although higher levels of MMP-9 and tissue inhibitor of matrix metalloproteinases-1 (TIMP-1) have been found in small series of patients with sepsis, MMP-10 levels have not been studied in this setting." (PMID 19799791, 2009). "In our larger study, we found significantly higher levels of TIMP-1, reduced MMP-9/TIMP-1 ratios, and nonsignificantly higher MMP-9 levels in sepsis patients than in healthy controls." (PMID 19799791, 2009). "As there was no regression between sepsis scoring and MMP-9 concentrations in plasma, quantification of MMP-9 in plasma cannot be recommended for clinical routine to aid the diagnosis of strangulating obstruction or to help with the decision for surgery, antibiotics, or euthanasia." (PMID 33488296, 2021). "As opposed to MMP-9, TIMP-1 levels are repeatedly reported to be higher in sepsis." (PMID 29861795, 2018). "Importantly, higher levels of MMP-9, but not MMP-2, were found in plasma of patients who did not survive sepsis." (PMID 29734352, 2018). "Moreover, higher levels of TIMP-1 (P < 0.001), reduced MMP-9 (P = 0.037), and a nonsignificant increase of MMP-10 were found in nonsurviving as compared with surviving sepsis patients." (PMID 19799791, 2009). "We bring forward now the potential role of collagenases (MMP-13 and MMP-1) and perhaps stromelysins (MMP-3) in sepsis, an interesting finding because these MMPs are neither expressed in neutrophils nor released from neutrophils granules after endotoxin challenge as MMP-8 and MMP-9 do5." (PMID 24833564, 2014).
Obesity (132 papers, 2008 to 2026). Accumulation of substantial excess body fat. "Clarified interpretation: Obesity is associated with increased circulating MMP-9 protein/activity and sometimes reduced adipose MMP-9 mRNA expression." (PMID 41227041, 2025). "In a study of Caucasian individuals with obesity, increased MMP9 expression in subcutaneous adipose tissue was associated with elastic fiber reduction within reticular dermis." (PMID 40806842, 2025). "Given the demonstrated ability of ITE to suppress LPS-induced MMP-9 expression through the inhibition of NF-κB and AP-1 signaling, future studies will explore its therapeutic potential in in vivo models of obesity-associated inflammation." (PMID 40565127, 2025). "In people with obesity, elevated MMP9 levels are associated with an increase in body mass index (BMI) and waist circumference." (PMID 39594522, 2024). "In the gelatinase subgroup, we have MMP-2 and MMP-9, also known as gelatinases A and B, respectively, which are associated with the practice of PA and obesity." (PMID 38470620, 2024). "Lipocalin-2 activates HSCs to secrete matrix metalloproteinase 9 (MMP9) in leptin-deficient obesity, thereby promoting the transition from simple steatosis to NASH." (PMID 38310315, 2024). "Socs3, Mmp9 and Prmt1, which had elevated expression levels in obesity that were reversed by weight loss, had decreased expression in ABA and remained decreased in WR." (PMID 37582711, 2023). "A cross-sectional study on infertile women with PCOS showed that circulating MMP-9 concentrations were increased only for those with obesity and PCOS, and that MMP-9 levels were associated with the duration of infertility." (PMID 35329952, 2022). "It was shown that obesity and an associated low-grade systemic inflammation modulates MMP-9 levels in children with OSA, independently from OSA severity." (PMID 32451401, 2020). "Growing evidence also suggests that circulating MMP-2 and MMP-9 levels could serve as potential biomarkers of low-grade inflammation and cardiovascular risk in obesity." (PMID 41227041, 2025). "Furthermore, MMP9's involvement in regulation of metaflammation associated with obesity, signifies another immuno-metabolic link at molecular level." (PMID 39281650, 2024). "In addition, LCN2 acts as a key mediator of HSC activation in leptin-deficient obesity via α-SMA/MMP9/STAT3 signaling, further exacerbating NASH." (PMID 37784089, 2023). "However, several human studies have linked MMP9 serum level with obesity-associated unhealthy metabolic state and insulin resistance." (PMID 37445827, 2023). "MMP9 encodes a zinc-dependent endopeptidase implicated in degrading extracellular matrix, immunity, and especially contributes to pathogenetic mechanisms involved in the development of obesity." (PMID 33777102, 2021). "MMP-9 is reported to be strongly associated with obesity and furthermore the presence of a high BMI has also been hypothesized to promote poor ovulation and thereby lesser chances of pregnancy." (PMID 32923927, 2020). "The association of MMP-9 with NO and duration of infertility indicates that high MMP-9 levels may cause endothelial dysfunction which might be responsible for complications in PCOS subjects with obesity." (PMID 32923927, 2020). "Taking that into account, our results underline the important role of insulin receptor-dependent regulation of MMP-9 in macrophages and further extend it to another hyperinsulinemia-related disease state i.e. the development of obesity-associated inflammation and insulin resistance." (PMID 20463885, 2010). "This understanding may indicate that a reduction in the expression of MMP-2 and MMP-9 after bariatric surgery could be a marker of clinical improvement in obesity, since a reduction in serum MMP levels is associated with a control of extracellular matrix function in adipocytes." (PMID 39766340, 2024).
Obesity (continued). "Hence, in this study, we investigated whether the changes in the secretion pattern of adipocytes (specifically under conditions mimicking obesity) caused changes in the expression of MMP-9." (PMID 38068928, 2023). "Moreover, the increased level of ceramide observed in obesity is associated with a decrease in the concentration of adiponectin, an increase in the secretion of pro-inflammatory cytokines and the up-regulation of MMP-9." (PMID 35745168, 2022). "In circulation, most studies demonstrate elevated MMP-9 protein and activity levels in obesity, which correlate with systemic inflammation (CRP, IL-6, TNF-α) and endothelial dysfunction." (PMID 41227041, 2025). "Findings on MMP-9 expression in obesity appear contradictory at first glance; however, these discrepancies largely reflect differences in tissue compartments and assay methods." (PMID 41227041, 2025). "A significant elevation of MMP-9 expression has been observed in inflammatory diseases, including obesity, cardiovascular diseases, tumor invasion, and rheumatoid arthritis." (PMID 40565127, 2025). "Matrix metalloprotease (MMP)-9 and lipopolysaccharide (LPS) are elevated in obesity, and both participate in the development of chronic low-grade inflammation in obese individuals." (PMID 40565127, 2025). "Matrix metalloproteinase-9 (MMP-9) and lipopolysaccharide (LPS) levels are known to be elevated in obesity and contribute to metabolic dysfunction." (PMID 40565127, 2025). "The RT-PCR results showed that stretching effectively inhibited the upregulation of mouse osteoclast genes Ctsk and MMP9 induced by obesity." (PMID 41278194, 2025). "Plasma MMP-9 levels were significantly elevated in the OSAS cohort (p = 0.0065) as well as in the obesity cohort (p = 0.0099)." (PMID 38172514, 2024). "MMP9 overexpression in obesity-exposed HME1 cells can explain increased cell invasiveness and motility." (PMID 38247865, 2024). "Individuals with obesity have also been observed to have an increase in MMP-9 levels, as evidenced by several studies." (PMID 38562155, 2024). "Within the context of obesity-induced airway remodeling, MMP-9 is suggested to be a key player in the development of airway fibrosis." (PMID 38562155, 2024). "Although studies on MMP9 levels in obesity have yielded varied results, it is well-acknowledged that MMP9 activity relates to inflammation and vascular abnormalities." (PMID 39594522, 2024). "This is in line with recent data which revealed a positive correlation of serum MMP-9 with the severity of OSAS50 and increased levels of pro-inflammatory MMP-9 that has been shown in the saliva of patients with obesity with non-alcoholic fatty liver disease." (PMID 38172514, 2024). "IL-6 is predominantly produced by infiltrated adipose tissue macrophages, while elevated MMP-2 and MMP-9 levels in obesity contribute to adipose tissue remodeling, triggering proinflammatory cytokine secretion and amplifying the inflammatory response." (PMID 38495901, 2024). "Current studies have shown higher levels of MMP-2 and MMP-9 in patients with obesity, metabolic syndrome, and T2DM compared to control groups." (PMID 39766340, 2024). "Among these hub genes, MMP9 was the only one that was differentially expressed and regulated by TFs in both obesity and PTC datasets." (PMID 37671970, 2023). "Our study also showed statistically significantly higher concentrations of MMP-9 in the saliva of subjects with obesity compared to those with normal body weight, both in women (p = 0.0451) and men (p = 0.0028)." (PMID 36835557, 2023). "Increased levels of MMP-2 and MMP-9 in subjects with obesity and type 2 diabetes, as well as obesity-related insulin resistance have been demonstrated in several studies." (PMID 37697354, 2023). "MMP-9 is mainly secreted by monocytes or macrophages, and contributes toward the pathogenesis of obesity-induced inflammation, insulin resistance, and cancer metastasis." (PMID 37658104, 2023).
Obesity (continued). "The findings of a positive correlation of MMP-9 levels with obesity, CYFIP1 mRNA with mood and autistic symptoms, and FMR1 mRNA expression level with better cognitive, language, and adaptive functions indicate potential biomarkers for specific FXS phenotypes." (PMID 37508583, 2023). "Tumor necrosis factor α (TNFα) was elevated in obesity and is involved in the induction of MMP-9 in monocytic cells." (PMID 37658104, 2023). "To conclude, the present study showed elevated levels of MMP-9 and MPO and reduced levels of MIF of PWS, which are altered beyond comorbid obesity and clinical cardiovascular risk factors." (PMID 37430349, 2023). "The administration of silymarin significantly inhibited the obesity-induced secretion of MMP-9, a marker of an aggressive phenotype." (PMID 35873545, 2022). "Our result also demonstrated that matrix metalloproteinase family members, MMP-2 and MMP-9, were potential targets of fucoidan against PFOA-associated obesity." (PMID 36034923, 2022). "Among these, MMP9 is involved in complications of obesity or metabolic syndrome through the breakdown of extracellular matrix (ECM) molecules." (PMID 36568118, 2022). "In the context of obesity and inflammation, elevated MMP2 expression and MMP9 activity are found in a mouse model of obesity and positively correlated with inflammatory cytokine expression." (PMID 34745017, 2021). "MMP-2 and MMP9 are the subclasses of metalloproteases involved in the development of obesity and insulin resistance, and indeed MMP-9 plasma levels are higher, despite lower protein levels in SM under HFD (60% fat) fed C57BL/6J mice." (PMID 33803198, 2021). "In conclusion, our results demonstrated that MMP-1, MMP-3 and MMP-9 levels were correlated with several obesity-related parameters including BMI, WC, blood pressure and endothelial-dependent response." (PMID 34625635, 2021). "Consistently, an increased expression of MMP9 in VAT was detected in patients with obesity and the treatment with DPT also increased its expression in adipocytes." (PMID 32283761, 2020). "For validation and further analysis of the endocrine mechanism from obesity, the expression of these related genes MMP9, AMPK, and YAP in the cultured TE-1 cells under different conditions was investigated." (PMID 33381605, 2020). "Obesity, inflammation and alterations in matrix metalloproteinase-9 (MMP-9) and nitric oxide (NO) levels are involved in the development of polycystic ovary syndrome (PCOS)." (PMID 32923927, 2020). "The simultaneous increase of MMPs and SMAD4-RUNX2 genes in T2D– patients with obesity is consequent, as MMP9 presents a direct target of RUNX2." (PMID 31866945, 2019). "The insulin resistant proinflammatory states of obesity and type 2 diabetes are characterized by an increase in IL-4, MMP-9, LIGHT, and CCR-2 expression in MNC and MMP-9 and NOM concentrations in plasma." (PMID 25642424, 2015). "We have recently shown that obesity and diabetes are associated with an increase in the expression of IL-4, LIGHT, CCR-2, and MMP-9 in MNC and that, following gastric bypass surgery, there is a reduction in the expression of these genes." (PMID 25642424, 2015). "A number of studies demonstrated that MMP-9 levels were higher in patients with obesity and in patients with metabolic syndrome as compared to patients with normal body weight." (PMID 25261984, 2015). "MMP2 and MMP9 exert a pivotal role in adipose tissue remodeling that occurs during the development of obesity." (PMID 24871103, 2014). "Functional MMP-9 gene polymorphism is strongly associated with obesity, and MMP-9 genotypes and haplotypes affect MMP-9 levels in obese children and adolescents." (PMID 23800102, 2013). "One of the key MMPs involved in adipogenesis is MMP9, which is down-regulated by insulin and, perhaps due to insulin resistance, raised in obesity [eg.25]." (PMID 20668691, 2010).